NUCLEOLIN (nucleolin multifunctional protein)
Description:
Nucleolin is the major nucleolar protein of growing eukaryotic cells. It is found associated with intranucleolar chromatin and pre-ribosomal particles. It induces chromatin decondensation by binding to histone H1. It is thought to play a role in pre-rRNA transcription and ribosome assembly. May play a role in the process of transcriptional elongation. Binds RNA oligonucleotides with 5'-UUAGGG-3' repeats more tightly than the telomeric single-stranded DNA 5'-TTAGGG-3' repeats.
Synonyms: NCL; C23; Nsr1
Tractability: Antibody: its Gene Ontology location is reachable by antibodies, with high confidence. PROTAC: UniProt records ubiquitination sites on it; ubiquitination databases record sites on it; its protein half-life has been measured.
Gene: Protein-coding gene on chromosome 2 (231,453,531 to 231,483,641, reverse strand). Ensembl gene ENSG00000115053.
Subcellular location: Nucleus, nucleolus; Cytoplasm
Subcellular location (Human Protein Atlas): Nucleoli; Nucleoli rim; Nucleoplasm; Mitotic chromosome
Pathways (Reactome):
Disease: Assembly and Release of Dengue Virus Virions; Respiratory syncytial virus (RSV) attachment and entry
Metabolism of RNA: Major pathway of rRNA processing in the nucleolus and cytosol
Gene Ontology:
Molecular function: DNA topoisomerase binding; identical protein binding; mRNA 5'-UTR binding; protein binding; RNA binding; telomeric DNA binding; insulin receptor substrate binding; nucleic acid binding; PH domain binding
Biological process: angiogenesis; negative regulation of translation; positive regulation of transcription of nucleolar large rRNA by RNA polymerase I; mRNA splicing, via spliceosome; regulation of gene expression; regulation of RNA metabolic process
Cellular component: cell cortex; chromosome; cytoplasmic ribonucleoprotein granule; extracellular exosome; membrane; nucleolus; nucleoplasm; nucleus; ribonucleoprotein complex; macropinosome membrane; plasma membrane; spliceosomal complex; cornified envelope; cytoplasm
Genetic constraint (gnomAD): Loss-of-function variants: 3 observed, 76.14 expected, observed/expected ratio (o/e) 0.0394, 90% interval 0.017 to 0.1. The upper end of that interval is the gene's LOEUF score, 0.1, which puts it in group 1 of 6, group 1 being the genes least tolerant of losing a copy. Missense variants: 756 observed, 888.45 expected, observed/expected ratio (o/e) 0.85, 90% interval 0.8 to 0.9. Synonymous variants: 342 observed, 308.95 expected, observed/expected ratio (o/e) 1.11, 90% interval 1.01 to 1.21.
Homologues: Orthologues: chimpanzee NCL (99% identical), macaque NCL (98% identical), dog NCL (92% identical), pig NCL (90% identical), rabbit NCL (89% identical), guinea pig NCL (88% identical), rat Ncl (83% identical), mouse Ncl (82% identical). Paralogues in human: HNRNPA3 (14% identical), HNRNPA1 (14% identical), HNRNPA1L2 (13% identical), HNRNPA1L3 (13% identical), HNRNPA2B1 (13% identical), HNRNPAB (13% identical), HNRNPD (13% identical), HNRNPDL (13% identical), RBM19 (13% identical), RBM39 (13% identical), MSI1 (12% identical), MSI2 (11% identical), and 24 more.
Diseases named in the same sentence as NUCLEOLIN in open-access papers:
NUCLEOLIN is named in the same sentence as 120 diseases in open-access papers, as found by Europe PMC text mining. Sharing a sentence is not in itself a finding about the gene and the disease.
NUCLEOLIN shares sentences with these, for which no sentence is quoted: cancer (96 papers); tumor (88); breast cancer (33); infection (21); glioma (11); hepatocellular carcinoma (11); gastric cancer (10); glioblastoma (8); prostate carcinoma (8); lung carcinoma (7); non-small cell lung carcinoma (7); cervical carcinoma (6); colon carcinoma (6); colorectal cancer (6); endometrial carcinoma (6); melanoma (6); neuroblastoma (6); acute myeloid leukemia (5); breast tumor (5); leukemia (5); triple-negative breast carcinoma (5); viral infection (5); COVID-19 (4); lung adenocarcinoma (4); metastatic disease (4); ovarian carcinoma (4); pancreatic ductal adenocarcinoma (4); autoimmune disease (3); liver cancer (3); lymphoma (3).
A further 90 diseases each share a sentence with NUCLEOLIN in 3 papers or fewer.